RAC1 (Rac family small GTPase 1)
Diseases named in the same sentence as RAC1 in open-access papers (continued):
Sharing a sentence is not in itself a finding about the gene and the disease.
glioma (continued). "The TWEAK-Fn14 ligand receptor axis-induced activation of Rac1 is one mechanism to enhance Rac1-GTP that is dependent upon a functional and activated Cdc42 protein; the depletion of Cdc42 abrogated glioma cell migration in vitro and invasion ex vivo." (PMID 24109588, 2013). "A role for Rac-1 in stemness and tumorigenicity had been previously reported for U87MG and U373 glioma cells and our results confirmed these findings with a significant reduction in clonogenic survival, sphere-forming capacity and glioma stem cell frequency when Rac-1 was knocked down." (PMID 38837899, 2024). "To precisely unravel the pathways that were related to the function of KIF4A in cytoskeletal remodeling of glioma, we hypnosis that whether KIF4A regulated F-actin through RhoA or Rac1/Cdc42." (PMID 36606197, 2022). "Interestingly, Rac1 and its downstream effector PAK1 have been reported to be involved in the maintenance of glioma stem-like cells and tumorigenicity in human glioma." (PMID 36230732, 2022). "The results obtained for both mRNA and protein levels indicate that TIAM1 is modulated by a functional circadian clock in LN229 glioma cells, while Rac1 showed a non-circadian expression at the mRNA level." (PMID 34371781, 2021). "In our study, knockdown of the expression of Rac1 in U87, U251, and T98G cells did not significantly affect cell viability, which indicates that Rac1 promotes glioma progression mainly by another way." (PMID 32585958, 2020). "In addition, p38, MAPK, phosphatidylinositol 3-kinase (PI3K), Rac1, Cdc42, and JNK-dependent pathways are important factors for lysophosphatidic acid (LPA) signaling, which is related to glioma cell migration." (PMID 30373180, 2018). "Studies have reported inhibition of Rac1 activity following overexpression of an IQGAP1 construct lacking a Rac1 binding site in HEK 293T cells and following RNAi-mediated silencing of IQGAP1 in U87MG glioma cells upon serum stimulation." (PMID 24355937, 2013). "Earlier report had shown that suppression of Rac1 induced apoptosis in human glioma cell but not in normal astrocytes." (PMID 23586025, 2013). "In addition, Arf6 is also found to form complexes with Rac1 and IQGAP1 in glioma cells upon HGF stimulation, and IQGAP1 is essential for Arf6-induced Rac1 activation and cell migration." (PMID 22701712, 2012). "Our results show that the effects of 1A-116, a drug designed to specifically inhibit the Rac1 signaling pathway by preventing its interaction with TIAM1, were also modulated by the circadian clock in LN229 cells in vitro and showed a time-of-day dependence in a glioma tumor model in vivo." (PMID 34371781, 2021). "RAC1 expression has previously been linked to transcription factor expression in glioma, and while the RNAseq data presented did not link ATF4 and XBP1 to RAC1 expression, the association may depend on cell type and genetic background." (PMID 29329780, 2018). "Moreover, inhibition of Rac1 activity via a dominant negative form of Rac1 induces apoptosis in primary and glioma cell lines, but not in normal adult astrocytes." (PMID 25243137, 2014). "Through inhibition of Rac1 activation, ATA inhibited the TWEAK-induced glioma cell invasion process but did not affect cell viability or TNFRSF12A expression." (PMID 33937046, 2021).
hepatocellular carcinoma (79 papers, 2010 to 2025). A malignant tumor that arises from hepatocytes. "Meanwhile, our data supported the concept that EGF is capable of inducing ERK and Rac1 activation through the Arf6 pathway, and this process is associated with hepatoma cell migration where GEP100 was present." (PMID 22701712, 2012). "RAC1 induction stimulates invasiveness of T-lymphoma cells and is associated with poor prognosis of hepatocellular carcinoma." (PMID 23342264, 2012). "Moreover, significant associations of Rac1 with poor prognostic parameters were demonstrated in other types of cancers including renal cell carcinoma, gastric cancer, and hepatocellular carcinoma." (PMID 39118792, 2024). "Recent literature has isolated certain NK cell subsets, including RAC1 high NK cells, which exhibit augmented tumor killing abilities in hepatocellular carcinoma (HCC) via regulating the STAT3-NKG2D axis." (PMID 41211067, 2025). "This work identified a novel small molecule ZYZ384 targeting SMYD3 with antitumor activity and impaired hepatocellular carcinoma tumor growth by reducing H3K4 trimethylation of the Rac1 promoter triggering the tumor cell cycle arrest through the AKT pathway." (PMID 39286779, 2024). "ZYZ384 targeted SMYD3 with antitumor activity and impaired hepatocellular carcinoma tumor growth by reducing H3K4 trimethylation of the Rac1 promoter triggering the tumor cell cycle arrest through the AKT pathway." (PMID 39286779, 2024). "Taken together, our study developed a novel molecule ZYZ384 targeting SMYD3 for hepatocellular carcinoma via reducing H3K4 trimethylation of the Rac1 promoter." (PMID 39286779, 2024). "Dis3L2 was found to be highly expressed in hepatocellular carcinoma tissues and promoted alternative splicing of the Rac1 gene through a nuclease-independent mechanism." (PMID 36823385, 2023). "MEL prevents hepatocellular carcinoma cell metastasis via inhibition of ras-related C3 botulinum toxin substrate 1 (Rac1), which participates in the c-Jun N-terminal kinase (JNK) and JNK-dependent cell motility processes and induces metastasis." (PMID 35053266, 2022). "Interference of YAP considerably reinforced autophagic flux by cumulating RAC1-driven ROS, which result in deactivation of mTOR in hepatocellular carcinoma cells." (PMID 35725558, 2022). "Rab23 promotes hepatocellular carcinoma cell migration via the Rac1/TGF-β signaling pathway and promotes squamous cell carcinoma cell migration and invasion by regulating the integrin β1/Tiam1/Rac1 pathway." (PMID 32605180, 2020). "TIPE1 can induce apoptosis in RAW264.7 and hepatocellular carcinoma cells by increasing the levels of Bcl‐2 family proteins or down‐regulating the Rac1 pathway." (PMID 32588529, 2020). "The lncRNA SchLAH (a seven-chromosome locus associated with hepatocellular carcinoma) is lowly expressed in HCC (hepatocellular carcinoma) and downregulates mRNA levels of RhoA and Rac1 in HCC cells." (PMID 31248165, 2019). "Studies have shown that TNFAIP8L1 can induce hepatocellular carcinoma cell apoptosis by interacting with Rac1." (PMID 31289124, 2019). "In contrast, in epidermoid carcinoma or liver carcinoma, downregulation of RAC1 results in a decrease in cisplatin sensitivity." (PMID 31314174, 2019). "A very recent study indicates that TIPE1 induces apoptosis by negatively regulating Rac1 activation in hepatocellular carcinoma cells." (PMID 28994231, 2018). "Recently, TIPE2 is proved to be an endogenous inhibitor of Rac1 in liver by which it suppressed invasion and metastasis of hepatocellular carcinoma (HCC)." (PMID 25946186, 2015). "In hepatocellular carcinoma cell lines PTK787 treatment reduced expression of migration-related proteins Rac1 and Rho and significantly inhibited cell migration at higher concentrations than studied herein (>20 μM)." (PMID 25340839, 2014).
hepatocellular carcinoma (continued). "Taken together, this study highlights the function of the PH domain of GEP100 and its regulated Arf6/ERK/Rac1 signaling cascade in EGF-induced hepatoma cell migration." (PMID 22701712, 2012). "Our results demonstrate that EGF stimulates hepatoma HepG2 cell migration through GEP100-dependent activation of the Arf6/ERK/Rac1 signaling pathway." (PMID 22701712, 2012). "A previous study has demonstrated that Rac1 activity corresponds with angiogenesis in hepatocellular carcinoma." (PMID 21980400, 2011). "The activation of Rac1 in hepatocellular carcinoma is correlated with VEGF expression and metastasis in vivo." (PMID 21980400, 2011). "Moreover, a direct inhibitory effect of A20 on the mTORC2/Akt/Rac1 signaling axis was found in hepatocellular carcinoma cells, due to the direct interaction between A20 and mTORC2 complex." (PMID 40719110, 2025). "Luteolin can regulate the mRNA expression of pro-proliferative genes, pro-apoptotic genes, and angiogenic molecules Uba2, VEGF, Fra-1, HIF-1α, and Rac1 in hepatocellular carcinoma HepG2 cells, thereby inhibiting the proliferative activity and angiogenesis of hepatocellular carcinoma cells." (PMID 37151401, 2023). "MEL inhibits the ras-related C3 botulinum toxin substrate 1 (Rac1), which participates in the c-Jun N-terminal kinase (JNK) and JNK-dependent cell motility processes and causes metastasis, preventing hepatocellular carcinoma cell metastasis." (PMID 35708464, 2022). "For example, miR-142 could directly target and negatively regulates RAC1 to suppress hepatocellular carcinoma cell migration and invasion; miR-101 acts as a novel suppressor by targeting RAC1 and inhibits the migration and invasion in thyroid cancer cells." (PMID 36045117, 2022). "In addition, TIPE2 inhibited invasiveness and tumor development via reducing MMP9 expression by targeting Rac1 in hepatocellular carcinoma (HCC) and gastrointestinal stromal tumor." (PMID 34249724, 2021). "To date, several studies have shown that TIPE1 can inhibit the activation of Rac1, its downstream target p65, and the c-Jun N-terminal kinase pathway in hepatocellular carcinoma cells and decrease mTOR phosphorylation by stabilizing TSC2 protein in a Parkinson's disease model." (PMID 31179241, 2019). "However, in epidermoid carcinoma and liver carcinoma cells, downregulation of RAC1 results in an increase in cisplatin resistance." (PMID 31314174, 2019). "Until now, only one study have shown that TIPE1 could induced hepatocellular carcinoma (HCC) cell apoptosis by targeting Rac1." (PMID 29108244, 2017). "Also, the INK4 Cdk-inhibitor p16 promotes cell migration in hepatocellular carcinoma cells through the activation of Rac1, although it has also been described that p16 plays a negative role on migration in other tumours." (PMID 27181366, 2016). "Indeed, the small GTPase Rac1 affects cell spreading, directed cell migration and lamellipodia formation, and has been identified as a regulatory target of miR-142-3p in hepatocellular carcinoma cells." (PMID 26657485, 2015). "Previous study of TIPE1 function on hepatocellular carcinoma (HCC) cells demonstrated that TIPE1 could induce apoptosis of HCC cells by negatively regulate the expression of Rac1." (PMID 26207809, 2015). "MiR-142a-3p has been shown to regulate RAC1 in hepatocellular carcinoma cells." (PMID 23285103, 2012). "RAC1 was shown to be a target of miR-142-3p in hepatocellular carcinoma cells." (PMID 23342264, 2012). "Compared to normal liver cells or human hepatocellular carcinoma (HCC) cell lines with low metastatic potential, HCC cell lines with high metastatic potential display increased mRNA and protein levels of Rac1." (PMID 31973181, 2020). "It has been demonstrated that Rac1 is a key molecule in regulating the invasiveness of PTC, and our previous research found that TIPE2 functions through inhibiting Rac1 in hepatocellular carcinoma (HCC) and non-small cell lung cancer (NSCLC)." (PMID 30186591, 2018).
hepatocellular carcinoma (continued). "This facilitates tumor cell migration and invasion, as seen in hepatocellular carcinoma, where IQGAP1 enhances Rac1-dependent Src/FAK signaling." (PMID 41035668, 2025). "RhoA and Rac1 have been demonstrated to stabilize the HIF-1α protein, suggesting the possible cross-talk between small G-proteins and HIF pathways in hepatocellular carcinoma." (PMID 39941828, 2025). "Rab23 is a member of the Ras-related small GTPase family, which can activate Rac1-TGFβ signal transduction and promotes EMT in hepatocellular carcinoma (HCC) cells." (PMID 38791951, 2024). "In hepatitis B virus (HBV)-associated hepatocellular carcinoma, the accumulation of ROS induced by HBV enhances the combination of IQGAP1 and Rac1, which activate the Rac1 and Src/FAK pathway to enhance anoikis resistance and the migration of hepatoma cells." (PMID 37049739, 2023). "In hepatocellular carcinoma cells, miR151 down-regulated the Rho GDP dissociation inhibitor α (RhoGDIA) coding transcript, and as a result RAC1, CDC42, and RHO were activated and cell migration was promoted." (PMID 37582765, 2023). "However, in other cases, STAT3 has been shown to act upstream of Rac1, for example in the mesenchymal type movement of hepatocellular carcinoma (HCC) cells." (PMID 32915198, 2020). "Although previous studies have shown that TIPE1 could induce apoptosis in hepatocellular carcinoma (HCC) cells by regulating Rac1, little is known about its structure." (PMID 26207809, 2015). "Current studies indicate that both Rac1 and Cdc42 regulate hypoxia inducible factor (HIF)-induced VEGF expression in response to hypoxia in human hepatocellular carcinoma and gastric cancer cell lines." (PMID 20067638, 2010). "SH3BP1 belongs to the Rho GTPase activating protein family and mediates cell motility 72, in a similar manner to that observed during EMT in prostate cancer, hepatocellular carcinoma (HCC) and cervical cancer via the Rac family small GTPase 1-WASP family member 2 pathway 73-75." (PMID 35982909, 2022). "Other MAPK members have been upregulated by HMGB1 including cell division control protein 42 homolog (Cdc42)/Ras-related C3 botulinum toxin substrate 1 (Rac1)/mitogen-activated protein kinase kinase 6 (MKK6)/p38 that led to the proliferation of human rhabdomyosarcoma and hepatocellular carcinoma." (PMID 32443845, 2020). "However, it was found in hepatoma cells that downregulating Arf6 expression suppressed the activity of its downstream effector Rac1 by attenuating the phosphorylation level of ERK1/2, which reduced the invasion and migration of hepatoma cells." (PMID 32822124, 2020). "However, MMP8 activity can also be harmful, as shown for pancreatic and gastric cancers, in which the interaction between MMP8 and Ephrin-B1 seems crucial, and hepatocellular carcinoma, where MMP8 was shown to activate the PI3K/Akt/Rac1 pathway." (PMID 31514474, 2019). "Moreover, our previous researches indicated that TIPE2 could inhibit Rac1 activation in innate immune cells and in human hepatocellular carcinoma (HCC)." (PMID 27556698, 2016). "In hepatitis B virus (HBV)-positive hepatocellular carcinoma (HCC), IQGAP1 is upregulated by increased reactive oxygen species (ROS) levels, which promotes its binding to Rac1 and subsequently activates the Src/FAK signaling axis." (PMID 41035668, 2025). "The upregulation of Rac1 expression can promote the lamellipodia formation of hepatoma cells, facilitating hepatocellular carcinoma (HCC) metastasis, and this may correlate with the Scar/Wave complex, which is the main downstream target of Rac1." (PMID 37049739, 2023). "Although Rac1 is targeted by miR-142-3p in hepatocellular carcinoma cells, we could not confirm altered expression at the protein level (results not shown)." (PMID 26657485, 2015).
hepatocellular carcinoma (continued). "Ras-related C3 botulinum toxin substrate 1 (RAC1) overexpressiosn and hyperactivation are correlated with aggressive growth and other malignant characteristics in a wide variety of cancers including hepatocellular carcinoma (HCC)." (PMID 35858925, 2022). "In hepatocellular carcinomas, it has been demonstrated that HIF-1α is not involved in the regulation of RhoA/ROCK and Rac1/PAK activity." (PMID 38791951, 2024). "In hepatocellular carcinoma CTHRC1 promotes cell adhesion through activation of integrin β1 and phosphorylation of focal adhesion kinase (FAK), while the activation of RhoA, but not Rac1 or Cdc42 plays a crucial role." (PMID 27430622, 2016).
prostate carcinoma (75 papers, 2009 to 2026). A carcinoma that arises from epithelial cells of the prostate gland. "Other forms of Rac1 mutants are also found in other tumors, such as the Rac1 (A159V) mutation common in Head and Neck Neoplasms and the Rac1 (Q61R) mutation in primary prostate cancer." (PMID 34079763, 2021). "Result showed that COL3A1 and SDC2 were found to be the highest risk factors of prostate cancer, followed by RAC1 and PTPRF." (PMID 34229299, 2021). "We have also previously shown that PTEN-deficient prostate cancer growth is at least partly driven through p110β-RAC1 activation in vivo." (PMID 33105713, 2020). "An exhaustive analysis of the mechanisms implicated in Rac1 hyperactivation revealed that this dysregulated signal is independent of P-Rex1 activity or other Rac-GEFs expressed in prostate cancer cells." (PMID 32092966, 2020). "Specifically, for prostate cancer, Rac1 signaling has been implicated in androgen receptor signaling leading to proliferation and epithelial-to mesenchymal transition (EMT)." (PMID 32092966, 2020). "Overexpression of RAC1 is frequently observed in oral, breast, gastric, testicular, and prostate cancers and increased RAC1 expression is positively associated with cancer progression." (PMID 30970654, 2019). "The present study indicates that PI3K, acting downstream of Rac1, has an essential role in the initiation of lamellipodial extension, which underlies prostate cancer cell invasion and metastasis." (PMID 24848679, 2014). "Together, these results indicate that 14-3-3ζ-Rac1 association is involved in lamellipodia formation in prostate cancer cells." (PMID 22808202, 2012). "Rac1 activity is associated with and appears to be essential for the metastatic phenotype of prostate cancer, as well as, other epithelial cancers." (PMID 23300597, 2012). "The Rho GTPase Rac1, which regulates cytoskeleton rearrangements necessary for cell migration, is strongly associated with aggressive prostate cancer." (PMID 23300597, 2012). "We found that a series of Plexin-B1 mutations in the hydrophobic interface, Trp1807GluPlex, Leu1815ProPlex (previously linked to prostate cancer), and Leu1815GluPlex, completely abolished its interactions with Rac1* and Rnd1." (PMID 21912513, 2011). "Finally, the interest of a Rac1 inhibitor to treat advanced chemoresistance prostate cancer, while reducing the risk of associated bladder dysfunction, is discussed." (PMID 35740379, 2022). "Western blots also failed to reveal RhoGDI1 and RhoGDI2 loss of expression in the aggressive prostate cancer cell lines that could have explained Rac1 and Cdc42 hyperactivation." (PMID 32092966, 2020). "One explanation for the observed hyperactivation of Rac1 in androgen-independent prostate cancer cells is that it could be the consequence of deficient expression of GAPs responsible for Rac1 inactivation." (PMID 32092966, 2020). "Moreover, castration-resistant prostate cancer cells, which have a high malignant potential associated with invasion and metastasis, overexpress Rac1." (PMID 24848679, 2014). "Thus, the p110β-RAC1 signaling axis may have important therapeutic implications for PTEN-deficient prostate cancer." (PMID 33105713, 2020). "In the present study, we determined the effects of Gαi2 on cell migration downstream of Rac1 activation and its effects on the activation of Wave2 and Arp 2/3 in prostate cancer cells." (PMID 40141305, 2025). "Peptide toxins such as JZTX-I, which activate Nav1.7, can upregulate the expression of cytoskeleton-related proteins and activate the Rho GTPases-RhoA/Rac1 signaling pathway in prostate cancer cells." (PMID 41163355, 2025). "The combination of Rac1 inhibitors and AR antagonists suppresses AR gene expression in androgen-sensitive prostate cancer cells." (PMID 40948788, 2025). "In this study, up-regulation of AKT activity was further maintained in organoid culture of prostate cancer tissue in crypt cultures isolated from the Rac1-FRET biosensor mouse." (PMID 37126544, 2023).